CAMK4 (calcium/calmodulin dependent protein kinase IV)
Description:
Calcium/calmodulin-dependent protein kinase that operates in the calcium-triggered CaMKK-CaMK4 signaling cascade and regulates, mainly by phosphorylation, the activity of several transcription activators, such as CREB1, MEF2D, JUN and RORA, which play pivotal roles in immune response, inflammation, and memory consolidation. In the thymus, regulates the CD4(+)/CD8(+) double positive thymocytes selection threshold during T-cell ontogeny. In CD4 memory T-cells, is required to link T-cell antigen receptor (TCR) signaling to the production of IL2, IFNG and IL4 (through the regulation of CREB and MEF2). Regulates the differentiation and survival phases of osteoclasts and dendritic cells (DCs). Mediates DCs survival by linking TLR4 and the regulation of temporal expression of BCL2. Phosphorylates the transcription activator CREB1 on 'Ser-133' in hippocampal neuron nuclei and contribute to memory consolidation and long term potentiation (LTP) in the hippocampus. Can activate the MAP kinases MAPK1/ERK2, MAPK8/JNK1 and MAPK14/p38 and stimulate transcription through the phosphorylation of ELK1 and ATF2. Can also phosphorylate in vitro CREBBP, PRM2, MEF2A and STMN1/OP18.
Synonyms: CaMK IV; CAMK; CAMK-GR; CAMKIV
Tractability: Small molecule: a structure with a bound ligand is known; a high-quality ligand is known; it has a high-quality binding pocket; it belongs to a druggable protein family. PROTAC: ubiquitination databases record sites on it; its protein half-life has been measured; a small molecule that binds it is known.
Target class: Protein Kinase; CAMK protein kinase group; Enzyme; CAMK protein kinase CAMK1 family; Kinase
Gene: Protein-coding gene on chromosome 5 (111,223,653 to 111,494,886, forward strand). Ensembl gene ENSG00000152495.
Subcellular location: Cytoplasm; Nucleus
Subcellular location (Human Protein Atlas): Nucleoli fibrillar center; Nucleoplasm; Endoplasmic reticulum
Pathways (Reactome):
Neuronal System: CREB1 phosphorylation through the activation of CaMKII/CaMKK/CaMKIV cascasde; Negative regulation of NMDA receptor-mediated neuronal transmission
Organelle biogenesis and maintenance: Transcriptional activation of mitochondrial biogenesis
Signal Transduction: CaMK IV-mediated phosphorylation of CREB
Gene Ontology:
Molecular function: calcium/calmodulin-dependent protein kinase activity; ATP binding; protein kinase activity; protein serine kinase activity
Biological process: long-term memory; myeloid dendritic cell differentiation; positive regulation of DNA-templated transcription; positive regulation of myeloid dendritic cell cytokine production; intracellular signal transduction; protein phosphorylation; regulation of osteoclast differentiation; regulation of T cell differentiation in thymus; signal transduction
Cellular component: extracellular exosome; fibrillar center; nucleoplasm; cytoplasm; nucleus
Genetic constraint (gnomAD): Loss-of-function variants: 6 observed, 10.78 expected, observed/expected ratio (o/e) 0.56, 90% interval 0.3 to 1.1. The upper end of that interval is the gene's LOEUF score, 1.1, which puts it in group 4 of 6, group 1 being the genes least tolerant of losing a copy. Missense variants: 285 observed, 317.82 expected, observed/expected ratio (o/e) 0.9, 90% interval 0.81 to 0.99. Synonymous variants: 122 observed, 128 expected, observed/expected ratio (o/e) 0.95, 90% interval 0.82 to 1.11.
Homologues: Orthologues: chimpanzee CAMK4 (99% identical), macaque CAMK4 (99% identical), pig CAMK4 (91% identical), rat Camk4 (81% identical), mouse Camk4 (81% identical), dog CAMK4 (79% identical), guinea pig CAMK4 (71% identical), tropical clawed frog camk4 (63% identical), zebrafish camk4 (62% identical). Paralogues in human: MKNK2 (26% identical), MAPKAPK5 (26% identical), MAPKAPK2 (26% identical), MAPKAPK3 (25% identical), MKNK1 (24% identical), DCX (12% identical).
Diseases named in the same sentence as CAMK4 in open-access papers:
CAMK4 is named in the same sentence as 117 diseases in open-access papers, as found by Europe PMC text mining. Sharing a sentence is not in itself a finding about the gene and the disease. The quoted sentences say what the papers report.
Hypertension (16 papers, 2012 to 2022). The presence of chronic increased pressure in the systemic arterial system. "They further reported that the loss of CaMK4 can markedly accelerate hypertension progression, accompanied by endothelial dysfunction and organ injury." (PMID 35958279, 2022). "For example, CAMK4 rs10491334 is associated with hypertension in Uyghur population; whereas GRK4 rs180105 in East Asians and Europeans; and GRK4 rs2960306 in Europeans." (PMID 34297769, 2021). "Other polymorphisms such as on gene CaMK4 (calcium/calmodulin-dependent kinase 4) which has a role in regulation of vascular tone also have been shown to be associated with hypertension." (PMID 24966013, 2014). "In this study, loss of the CaMK4 gene resulted in endothelial dysfunction, hypertension, and related complications in mice." (PMID 24103216, 2013). "The fact that CAMK4 rs10491334 associates also with hypertension is reassuring in that hypertension and longevity are regulated by common pathways." (PMID 22524405, 2012). "Moreover, previous studies have found that some important polymorphisms such as PlA2, CaMK4, and G-protein-coupled receptor kinase are linked to hypertension and stroke." (PMID 29642209, 2018). "However, a recent genome-wide analysis indicated an association between hypertension and a single-nucleotide polymorphism (rs10491334) of the human CaMKIV gene (CaMK4), which suggests a role for this kinase in the regulation of vascular tone." (PMID 23130158, 2012). "Previous studies have confirmed that the CAMK4 gene was closely related to human longevity and hypertension and regulated the immune response by activating transcription factors to regulate gene expression in immune cells." (PMID 34367468, 2021). "Impairment of CaMK-mediated activation of eNOS, as in CaMK4 gene deletion, induces hypertension, as demonstrated by the fact that CAMK4_/_ mice display a hypertensive phenotype that leads to typical organ damage." (PMID 26911143, 2016). "To directly assess the role of CaMKIV in hypertension, we characterized the cardiovascular phenotype of CaMK4−/− mice." (PMID 23130158, 2012). "Furthermore, calcium/calmodulin-dependent kinase 4 (CaMK4) gene deletion can impair CaMK-mediated activation of eNOS, which induces hypertension in the mice null for CaMK4." (PMID 26805877, 2016). "Impairment of CaMK-mediated activation of eNOS, as in CaMK4 gene deletion, induces hypertension." (PMID 24053183, 2013). "The results gained in the CaMK4−/− mouse show a role for this kinase in the setup of hypertension." (PMID 23130158, 2012). "In our model, endothelial dysfunction could be either primitive to hypertension or, alternatively, secondary to the hypertensive state of CaMK4−/− mice." (PMID 23130158, 2012).
lupus (16 papers, 2017 to 2026). "We previously showed that genetic CaMK4 deficiency suppresses autoimmunity and nephritis in lupus-prone mice." (PMID 41977373, 2026). "Here, the authors demonstrate that CaMK4 expression controls the differentiation of T follicular helper cells, leading to the expansion of pathogenic B cells in systemic lupus erythematosus." (PMID 38287012, 2024). "To evaluate the relevance of our findings in autoimmunity, we crossed the B6.lpr with the Camk4fl/fl.dlck-Cre mouse to generate a T cell-specific, Camk4-deficient lupus-prone mouse." (PMID 38287012, 2024). "CaMK4 expression of SLE T cells is upregulated and CaMK4-deficient lupus mice show amelioration of autoimmunity with decreased TH17 and increased Treg cell numbers." (PMID 29755456, 2018). "In the B6.lpr lupus-prone mouse, the deletion of Camk4 in T cells leads to the reduction of circulating and tissue Tfh cells, decreased levels of multiple pathogenic B cell subsets, and improvement of biological and clinical hallmarks of the disease." (PMID 38287012, 2024). "Targeted delivery of a CaMK4 inhibitor to podocytes preserved their ultrastructure, averted immune complex deposition and crescent formation, and suppressed proteinuria in lupus-prone mice, despite systemic autoimmunity remaining intact." (PMID 35333675, 2022). "We previously demonstrated that calcium/calmodulin kinase IV (CaMK4) expression is increased in podocytes of lupus prone MRL/lpr mice and that exposure of cultured human podocytes to IgG from individuals with SLE leads to CaMK4 upregulation." (PMID 33784256, 2021). "The expression of calcium/calmodulin kinase IV (CaMK4) is increased in podocytes of patients with LN and lupus-prone mice, and its podocyte-targeted inhibition averts the development of nephritis in mice." (PMID 33784256, 2021). "We have shown that antibodies present in lupus sera enter podocytes to upregulate CaMK4, which in turn compromises their structure and function, and that treatment targeting this molecule only in the podocyte prevents LN in mice." (PMID 33784256, 2021). "Inhibition of CaMK4 in lupus-prone models prevent proteinuria and preserve podocyte ultrastructure through the inhibition of synaptopodin degradation." (PMID 31470591, 2019). "In lupus-prone mice, targeted delivery of a CaMK4 inhibitor to CD4+ T cells suppresses both autoimmunity and the development of nephritis." (PMID 30333818, 2018). "Increased CaMK4 activity causes increased expression and activity of CREMα in T cells from patients with SLE and lupus-prone mice." (PMID 30333818, 2018). "In the MRL/lpr lupus-prone mouse, depletion of CaMK4 restores serum levels of IL-2 as well as Treg cell numbers and function." (PMID 30333818, 2018). "Aberrant activation of CaMK4 contributes to T cell abnormalities in systemic lupus erythematosus (SLE), a chronic systemic autoimmune disease presenting with diverse clinical manifestations." (PMID 30333818, 2018). "In lupus-prone mice, targeted delivery of a CaMK4 inhibitor suppresses both autoimmunity and the development of nephritis." (PMID 30333818, 2018). "T cells from SLE patients and lupus-prone mice have abnormally high expression of CaMK4, which activates the AKT-mTOR pathway to promote Th17 cell development and IL-17 release.Th17 cell differentiation can be considerably decreased by blocking the CaMK4-AKT-mTOR pathway." (PMID 41476956, 2025). "Genetic or pharmacologic inhibition of CaMK4 prevents development of nephritis in lupus-prone mice." (PMID 33784256, 2021). "Moreover, Ca2+/calmodulin-dependent protein kinase IV (CaMK4) is upregulated in LN patients and lupus-prone models." (PMID 31470591, 2019). "Calcium calmodulin kinase IV (CaMK4) regulates multiple processes that significantly contribute to the lupus-related pathology by controlling the production of IL-2 and IL-17 by T cells, the proliferation of mesangial cells, and the function and structure of podocytes." (PMID 30333818, 2018).
lupus (continued). "CaMK4 is increased in T cells of patients with systemic lupus erythematosus (SLE) and is required for Th17 cell differentiation." (PMID 35869084, 2022). "Activation of CaMK4 is increased in T cells from patients with SLE and lupus-prone MRL/lpr mice." (PMID 30333818, 2018). "Moreover, administration of the CaMK4 inhibitor KN93 sufficiently expanded Tregs in vivo and alleviated disease in lupus-prone mice." (PMID 29755456, 2018). "In the absence of CaMK4 in T cells, germinal center formation and humoral immunity is impaired in immunized mice, resulting in reduced anti-dsDNA titres, as well as IgG and complement kidney deposition in the lupus-prone B6.lpr mouse." (PMID 38287012, 2024).
Anxiety (10 papers, 2005 to 2026). Intense feelings of nervousness, tension, or panic often arise in response to interpersonal stresses. "Also, Camk4 downregulation has been linked to disrupted synaptic plasticity, learning deficits and anxiety in rodents." (PMID 41039100, 2026).
depression (8 papers, 2007 to 2025). "Depression-like behavior of Camk4−/− mice in comparison with wild-type animals is accompanied by a combination of disturbances in the hippocampal dentate gyrus, including inhibition of neurogenesis and a decrease in the activation of BDNF signaling pathway." (PMID 32992988, 2020).
Autoimmunity (7 papers, 2018 to 2026). The occurrence of an immune reaction against the organism's own cells or tissues. "In the current study, we have demonstrated that T cell-specific CaMK4 expression drives Tfh cell expansion and, ultimately, humoral immune response during immunization and nominal antigens and autoimmunity." (PMID 38287012, 2024). "Here, we show that T cell-specific expression of calcium/calmodulin-dependent protein kinase IV (CaMK4) leads to T follicular helper (Tfh) cells expansion in models of T-dependent immunization and autoimmunity." (PMID 38287012, 2024). "It was shown that SLE T cells are characterized by increased CAMK4 activity, while Camk4 global knockdown improves autoimmunity in mice." (PMID 38474381, 2024). "In conclusion, this study identifies CaMK4 activation in T cells as a major factor responsible for the expansion of T follicular helper cells and a full-blown T-dependent humoral response in the setting of immunization and autoimmunity." (PMID 38287012, 2024). "Interestingly, inhibition of CaMK4 — in podocytes only — prevents immune complex deposition and preserves renal function, despite systemic autoimmunity remaining intact." (PMID 33784256, 2021). "CaMK4 is responsible for regulation of CD86 in podocytes, along with other cytokines that are key players in autoimmunity." (PMID 33784256, 2021). "Calcium/calmodulin-dependent protein kinase IV (CaMK4) has been shown to be involved in autoimmunity but it is not clear how it functions in psoriasis." (PMID 35869084, 2022).
autoimmune disease (6 papers, 2015 to 2025). A disorder resulting from loss of function or tissue destruction of an organ or multiple organs, arising from humoral or cellular immune responses of the individual to their own tissue constituents. "CaMK4 promotes the differentiation of Th17 cells and the production of IL-17, and this cytokine is a key factor in IL-17-associated autoimmune diseases, such as SLE, EAE, and psoriasis." (PMID 35869084, 2022). "Psoriasis is also an IL-17-associated autoimmune disease, and the mechanism by which CaMK4 affects psoriasis remains unknown." (PMID 35869084, 2022). "Calcium/calmodulin-dependent protein kinase IV (CaMK4) plays a key role in autoimmune diseases, significantly affecting genes involved in immune response and inflammation." (PMID 40362523, 2025). "CaMK4 has an important function in autoimmune diseases, and the contribution of CaMK4 in psoriasis remains obscure." (PMID 35869084, 2022). "The increased expression of one essential target (calcium/calmodulin-dependent protein kinase IV, CAMK4) was necessary for Th17 cell differentiation that was correlated to tissue inflammation in several autoimmune diseases, including SLE42." (PMID 26560501, 2015). "Furthermore, genetic deletion or pharmacologic inhibition of CaMK4 ameliorates Th17 cell-mediated autoimmune diseases, such as experimental autoimmune encephalomyelitis (EAE) and lupus-like disease in mice." (PMID 35869084, 2022). "In vitro experiments indicated that CaMK4 inhibition may serve as a therapeutic strategy for Th17-driven autoimmune diseases." (PMID 33245101, 2020).
influenza (6 papers, 2018 to 2025). An acute viral infection of the respiratory tract, occurring in isolated cases, in epidemics, or in pandemics; it is caused by serologically different strains of viruses (influenzaviruses) designated A, B, and C, has a 3-day incubation period, and usually lasts for 3 to 10 days. "Similar utilisation of systems biology has been applied to groups of interest, such as older adults, where one study validated the identification of genes, including CAMK4, previously associated with influenza vaccine responses." (PMID 33198297, 2020). "They observed that the day 3 expression of CAMK4 in PBMCs from individuals immunized with the inactivated influenza vaccine negatively correlated with the vaccinal antibody response at day 2822." (PMID 38287012, 2024). "Furthermore, CAMK4 was identified as one of the top genes of a geneset/cluster (linked to T cell activation) that was associated with reduced cellular immune responses (IFN-γ, IL-2 cytokine secretion) after influenza vaccination in 138 healthy older adults." (PMID 36560767, 2022).
leukemia (6 papers, 2015 to 2025). A malignant (clonal) hematologic disorder, involving hematopoietic stem cells and characterized by the presence of primitive or atypical myeloid or lymphoid cells in the bone marrow and the blood. "Both Camk1 or Camk4 knockdown significantly prolonged the survival of xenografted mice and greatly inhibited leukemia development as determined by analysis of knockdown cells, human leukemic hCD45+ cells, and spleen size." (PMID 29482582, 2018). "Next, we tested the in vivo effect of knockdown of CAMK1 or CAMK4 expression in MV4-11 leukemia cells in transplanted NOD/SCID-IL2RG (NSG) mice." (PMID 29482582, 2018). "For example, in human promyelocytic leukemia cells, mouse pancreatic β cells, and bone marrow hematopoietic stem cells, CaMK4 exhibits an inhibitory effect on proliferation; whereas in mouse Tfh cells, renal cystic epithelial cells, and liver cancer cells, it promotes proliferation." (PMID 41227414, 2025). "The knockdown of CAMK1 or CAMK4 in AML cell lines including MV4-11 cells and KASUMI-1 led to significant inhibition of cell growth, indicating that CAMKs are functionally essential for human leukemia cells." (PMID 29482582, 2018).
liver cancer (6 papers, 2019 to 2025). An epithelial or non-epithelial malignant neoplasm that arises from the liver. "MiR-129-5p represses the growth of liver cancer cells via regulating calcium/calmodulin-dependent protein kinase 4 (CAMK4) and thus suppresses the activation of mitogen-activated protein kinase (MAPK) signaling." (PMID 34660566, 2021). "Wound healing assay and transwell assay were performed to help explore the effects of CAMK4 on the metastatic potential of liver cancer cells." (PMID 31624237, 2019). "The results of this study showed that the effects of overexpression of CAMK4 on liver cancer cell lines were relatively insignificant." (PMID 31624237, 2019). "To further demonstrate the inhibitory effects of CAMK4 on liver cancer cells, we constructed CAMK4-overexpressing HepG2 and BEL-7402 cells by plasmid transfection and named control group, NC group, and CAMK4 group, respectively." (PMID 31624237, 2019). "CAMK4 was a direct target for miR-129–5p and was lowly expressed in liver cancer tissues and cells." (PMID 31624237, 2019). "Moreover, the downregulation of miR-129-5p reduced the levels of CAMK4 protein and mRNA in liver cancer cells." (PMID 31624237, 2019). "Further studies have shown that upregulation of CAMK4 expression could significantly induce apoptosis and inhibit proliferation of liver cancer cells, and that CAMK4 had partial anti-migration effects." (PMID 31624237, 2019). "Therefore, the results of this study demonstrated that miR-129-5p could inhibit the proliferation of liver cancer cells and promote apoptosis by targeting directly CAMK4 and inhibiting the activation of the MAPK pathway." (PMID 31624237, 2019). "A similar phenomenon is observed in liver cancer cells, where miR-129-5p inhibits the MAPK pathway by targeting the calcium calmodulin-dependent protein kinase IV (CAMK4) to reduce tumor progression." (PMID 35954293, 2022). "Thus, miR-129-5p and CAMK4 could be used as a potential target for the treatment of liver cancer." (PMID 31624237, 2019).
nephritis (5 papers, 2018 to 2026). Inflammation of renal tissue. "Therefore, we sought to determine whether the expression of CaMK4 in urine podocytes reflects active nephritis in patients with SLE." (PMID 33784256, 2021).